CCR2 (C-C motif chemokine receptor 2)
Diseases named in the same sentence as CCR2 in open-access papers (continued):
Sharing a sentence is not in itself a finding about the gene and the disease.
nephrolithiasis (2 papers, 2017 to 2025). The presence of a calculus in the pelvis of the kidney; this is most often composed of mineral salts and proteins. "Therefore, we proposed that, in the process of kidney stone formation, the overexpression of CCR2 mediated by relevant miRNAs, such as rno-miR-192, rno-miR-194, and rno-miR-499, would induce the inflammation and damage to the renal tubular epithelial cells and promote nephrolithiasis." (PMID 29392139, 2017). "In glyoxylic acid-induced nephrolithiasis murine models, CCR2 inhibitors significantly reduce tubular epithelial injury and crystal deposition, likely through disrupting the CCL2/CCR2-axis-mediated cross-talk between crystal-laden tubular cells and pro-inflammatory macrophages." (PMID 40867535, 2025).
orchitis (2 papers, 2022 to 2025). Inflammation of one or both testes due to viral or bacterial infections. "It is well established that blocking monocyte recruitment by CCR2 KO or clodronate-mediated depletion notably reduces tissue destruction and fibrosis in experimental orchitis models, but the TM subgroups that regulate these events during infection-induced inflammation remain poorly defined." (PMID 41031892, 2025). "Indeed, earlier studies have shown that CCR2-KO mice exhibit a marked reduction in immune cell infiltration, fibrosis severity, and tissue damage in this model, suggesting that targeting CCR2+ monocyte-macrophage infiltration could be a potential therapeutic strategy for UPEC-orchitis." (PMID 41031892, 2025).
preeclampsia (2 papers, 2020 to 2025). Preeclampsia is a hypertensive disorder of pregnancy that is characterized by new-onset hypertension with proteinuria presenting after 20 weeks of gestation, and depending on mild or severe forms may initially present with severe headache, visual disturbances, and hyperreflexia. "CCR2 are involved in Th1 and Th2 immunity activation which might contribute to the development of preeclampsia." (PMID 32566660, 2020). "Cardiac gene expression of Vcam, Edn1, Ccr2, Ctgf, Tgfb1, Tgfb2, Tgfb3, Bnp, Cybb, Mmp2, Mmp9, Timp1, Camk2a, Slc9a1, Nr3c2, and Nr3c1 was not different between mice who had a normal pregnancy and mice who had a preeclampsia-like pregnancy at 5 or 10 weeks postpartum (respectively)." (PMID 40425613, 2025).
prion disease (2 papers, 2014 to 2020). A transmissible disease that is caused by a protein that is able to induce abnormal folding of normal cellular proteins, leading to characteristic spongiform brain changes, which are associated with neuronal loss without an inflammatory response. "We next aimed to address the impact of CCR2 deficiency on the generation of the microglial inflammatory response in prion disease." (PMID 24648328, 2014). "Given the results regarding microglial activation in response to prion disease upon CCR2 deficiency, we wanted to analyze its impact on the astroglial response." (PMID 24648328, 2014). "The transcription factor underlying microglial proliferation in prion disease, PU.1, is similarly expressed in both WT and CCR2−/− mice, and is upregulated in response to prion disease." (PMID 24648328, 2014). "The evidence reported here shows that there is minimal impact of CCR2 deficiency on prion disease." (PMID 24648328, 2014). "Given the recent evidence that the Ly-6ChiCCR2+ population of circulating monocytes infiltrates the brain during pathology in a CCR2-dependent manner, we analyzed the progression of prion disease in CCR2−/− mice." (PMID 24648328, 2014). "The microglial population (Iba-1+ cells) expanded to similar levels in the hippocampus (HC) of WT and CCR2−/− mice, in response to prion disease (ME7), when compared with NBH controls." (PMID 24648328, 2014). "Both CCL2 and CCR2 are upregulated in prion disease, as reported in the present work and previously, indicating a potential role for of this receptor-ligand interaction." (PMID 24648328, 2014). "We observe a similar expansion of the microglial pool (Iba1+ or PU.1+ cells) in response to prion disease in mice with a WT or CCR2−/− background." (PMID 24648328, 2014). "The expression of CSF1 and its receptor CSF1R show similar patterns, appearing upregulated in prion disease, with the CCR2−/− background having a less pronounced effect." (PMID 24648328, 2014). "The behavioral course of prion disease is also characterized by a phase of hyperactivity, observed at similar levels in WT or CCR2−/− ME7-animals and identified by an increase in the distance travelled and the ambulatory counts in the open field task." (PMID 24648328, 2014). "We have studied the potential contribution of circulating monocytes or progenitors to the pool of macrophages/microglia in prion disease, using tracing techniques and investigated the role of CCR2 in the cell populations' dynamics." (PMID 24648328, 2014). "Deficiency in the monocyte chemokine receptor CCR2 does not affect microglia abundance or CNS prion disease, indicating that the microglial expansion that occurs during prion disease is a consequence of the local proliferation of CNS-resident cells." (PMID 33023255, 2020). "Similar results were obtained for the expression of the anti-inflammatory cytokine TGFβ, found to be upregulated in response to prion disease, independent of the deficiency of CCR2." (PMID 24648328, 2014). "This is indicated by the fact that abolishing the expansion of the perivascular macrophage population in response to prion disease in CCR2 deficient mice had no impact over the progression of the pathology." (PMID 24648328, 2014). "A deficiency in CCR2, and thus the absence of recruitment of circulating monocytes, does not impact microglial dynamics, the inflammatory profile or the temporal behavioral course of prion disease." (PMID 24648328, 2014). "The expression of the marker of M2-like inflammatory activation, YM1, was in accord with previously reported data, showing non-significant change with prion disease, and these results were not differentially affected by the WT or CCR2−/− background." (PMID 24648328, 2014). "The transcription factors RUNX1 and IRF8, involved in the proliferation and lineage commitment of microglia, were found to be upregulated in animals with prion disease, with no differential effect of the CCR2−/− background." (PMID 24648328, 2014).
rectal cancer (2 papers, 2022 to 2024). A primary or metastatic malignant neoplasm that affects the rectum. "Comparison of monocytes from patients with colon and rectal cancer showed decrease in CD14-CD16+CCR2+ in rectal cancer (fold change 2,4), however statistical significance has not been reached." (PMID 36733385, 2022). "CD14-CD16+CCR2+ subpopulation can be predictive for bad NAC response in rectal cancer." (PMID 36733385, 2022). "In patients with rectal cancer, who had the percentage of CD14+CD16+CCR2+ monocytes below 20% out of CD14+CD16+, the percentage of CD14+CD16+CCR2+ was increased after NAC (in 6 out of 7 patients tested)." (PMID 36733385, 2022). "Here we have identified biological valid differences in the distribution of CCR2 and CD163 expression on monocytes among colon and rectal cancer patients." (PMID 36733385, 2022). "In summary, we have identified biological valid differences in the distribution of CCR2 and CD163 expression among colon and rectal cancer patients." (PMID 36733385, 2022). "In summary, we found that in patients with rectal cancer increased amount of CCR2+ monocytes was indicative for the absence of both lymphatic and hematogenous metastasis." (PMID 36733385, 2022). "We demonstrated that in patients with rectal cancer increased percentage of CCR2+ monocytes was indicative for the absence of both lymphatic and hematogenous metastasis." (PMID 36733385, 2022). "In patients with rectal cancer, increased amount of CCR2+ monocytes was indicative for the absence of both lymphatic and hematogenous metastasis." (PMID 36733385, 2022). "The major finding is both NAC and surgical intervention affect proportion of CCR2+ and CD163+ monocytes within non-classical CD14-CD16+ and CD14+CD16+ subsets in patients with CRC, and the effects are specific for colon and rectal cancer patients." (PMID 36733385, 2022). "Both NAC and surgical intervention affected proportion of CCR2+ and CD163+ monocytes within non-classical CD14-CD16+ and CD14+CD16+ subsets in patients with CRC, and effects were specific for colon and rectal cancer patients." (PMID 36733385, 2022).
renal dysfunction (2 papers, 2016 to 2025). "Elevated CCR2 expression in monocytes has been linked to conditions such as renal dysfunction, cardiovascular disease, or HIV-associated neurocognitive disorders (HANDs)." (PMID 40362169, 2025). "In this work, the highest levels of IL-6, CCL2 gene expression and IL-10 release and the lowest transcript levels of CCR2, which reflects monocyte maturation, have been observed after treatment with IS at concentrations found in subjects with moderate renal dysfunction." (PMID 26925780, 2016).
Retinal atrophy (2 papers, 2013 to 2019). A nonspecific term denoting wasting, especially as a result of degeneration, of the retinal pigment epithelium (RPE) and neurosensory retinal cells. "Since our mice do not have Crb-1 rd8 mutation, our results suggest that the deletion of Ccl2 and Cx3cr1 predisposes mice to retinal atrophy under aging and chronic light damage conditions more so than in the single CCL2 or CCR2 knockout mice." (PMID 23637822, 2013). "These CCR2+ monocytes infiltrate, accumulate, and participate in development of retinal atrophy; and the authors showed that pharmaceutical inhibition of the CCL2-CCR2 axis halts atrophy." (PMID 31428180, 2019).
retinal detachment (2 papers, 2013 to 2023). An eye emergency condition which may lead to blindness if left untreated. "It has also been shown that photoreceptor loss after retinal detachment or light-induced degeneration can be attenuated by ablation of CCL2 or CCR2 signalling by reducing recruitment of ED1 and Iba1 positive cells." (PMID 23232206, 2013).
Salmonella Infections (2 papers, 2024). Infections with bacteria of the genus SALMONELLA. "(C–E) RT-qPCR analysis of mRNAs encoding inflammatory cytokines (Tnfα, Il1β, and Il6), chemokines (Ccr2, Ccl2, Cxcl1, and Cxcl10) and macrophage biomarkers (Nos2 and Arg1) in BMDMs measured at the indicated times after Salmonella infection (multiplicity of infection [MOI] = 1) (n = 5)." (PMID 39475776, 2024).
scleroderma (2 papers, 2023 to 2024). Scleroderma is a rare autoimmune connective tissue disorder characterized by abnormal hardening of the skin and, sometimes, other organs. "A study indicates that enriched genes including MPO (myeloperoxidase), RXFP1, CXCL11, CTNND2, BMPR2, TLR3, CCR2, and CAV1 are altered expressed in scleroderma." (PMID 38137330, 2023).
scrapie (2 papers, 2016 to 2017). A fatal disease of the nervous system in sheep and goats, characterized by pruritus, debility, and locomotor incoordination. "Most strikingly LACV had a strong increase in Ccr2 correlating with leukocyte infiltration, which was not seen in scrapie or BE." (PMID 27046083, 2016).
skin cancer (2 papers, 2021 to 2025). "CXCL17, CCR2, and CCL5 mRNA levels were significantly decreased in skin tumors of CCL17 TG mice compared with WT mice." (PMID 33670758, 2021).
syphilis (2 papers, 2020 to 2023). A contagious bacterial infection caused by the spirochete Treponema pallidum. "Currently, the dynamic changes of CCR2 and CX3CR1 on monocyte subsets during HIV-1 and syphilis coinfection have not been fully investigated." (PMID 32626718, 2020).
Thrombocytopenia (2 papers, 2008 to 2010). A reduction in the number of circulating thrombocytes. "The degree of thrombocytopenia and hemoconcentration was similar in WT and CCR2–/– mice, but levels of IL-6 and IFN-γ, but not TNF-α, were decreased systemically in infected CCR2–/– mice." (PMID 21206747, 2010).
thyroid cancer (2 papers, 2021 to 2025). "Mice were treated with doxycycline for one week to develop thyroid cancer, and the expression levels of CCL2, CSF-1, LGALS3BP, INPP5D and CCL7, together with that of the chemokine receptors CCR2 and CSF1R, were measured in cancer specimens by quantitative RT-PCR." (PMID 34299284, 2021).
trigeminal neuralgia (2 papers, 2012 to 2013). Trigeminal neuralgia is a nerve disorder that causes a stabbing or electric-shock-like pain in parts of the face. "Targeting the CCL2/CCR2 pathway may provide a novel therapeutic approach for the treatment of the trigeminal neuralgia." (PMID 22721162, 2012).
vitamin D deficiency (2 papers, 2017 to 2023). A nutritional condition produced by a deficiency of VITAMIN D in the diet, insufficient production of vitamin D in the skin, inadequate absorption of vitamin D from the diet, or abnormal conversion of vitamin D to its bioactive metabolites. "In univariate logistic regression models, we found that increased expression of CX3CR1+ (p <0.01) and decreased expression of CCR2+ (p < 0.01) were significantly associated with vitamin D deficiency." (PMID 28464004, 2017). "After adjustment, greater expression of CX3CR1 and lower expression of CCR2 remained significantly associated with vitamin D deficiency." (PMID 28464004, 2017). "In fully adjusted models associations with vitamin D deficiency persisted for CCR2+ and CX3CR1+." (PMID 28464004, 2017). "Among patients with vitamin D deficiency, we also found higher percentages of patrolling monocytes (CD14dimCD16+), which typically express high levels of CX3CR1, and lower percentages of the classical monocyte subset (CD14++CD16-) that typically express CCR2 overall." (PMID 28464004, 2017).
abortion (1 paper, 2024). the ending of pregnancy by removing a fetus or embryo before it can survive outside the uterus. "In the Monocyte group, the following immunophenotypes all have negative causal relationships with abortion: Monocyte AC and CCR2 on CD14+ CD16+ monocyte were negatively associated with abortion (OR < 1)." (PMID 39388432, 2024).
allergic contact dermatitis (1 paper, 2023). An inflammatory skin condition caused by an immune response to direct contact between the skin and an allergen. "For instance, in an animal model of allergic contact dermatitis, it has been shown that CCR2/CC-chemokine ligand 2 (CCL2) signaling is activated in skin neurons that promote itch behavior." (PMID 38116004, 2023).
amebiasis (1 paper, 2020). A parasitic infectious disorder caused by amoebas. "Moreover, gonadectomy and testosterone substitution in male mice replicated the original sex differences observed in the murine model of amebiasis with respect to cytokine expression, the percentage of classical monocytes, and surface marker expression of classical monocytes except that of CCR2." (PMID 32651360, 2020).
aneurysmal disease (1 paper, 2025). "Using the CCR2 PET/CT radiotracer, we observed that CCR2 signal intensity increased in the aortic wall of AAA patients, particularly in those with advanced aneurysmal disease." (PMID 40365294, 2025).
Aortic dissection (1 paper, 2018). Aortic dissection refers to a tear in the intimal layer of the aorta causing a separation between the intima and the medial layers of the aorta. "Lacking either IL-6 or MCP-1 receptor CCR2 will reduce the early onset of aortic dissections." (PMID 29967801, 2018).
autism (1 paper, 2025). Persistent deficits in social interaction and communication and interaction as well as a markedly restricted repertoire of activity and interest as well as repetitive patterns of behavior. "Third, through network toxicology, single-cell transcriptomics, and animal experimentation, we demonstrate that chronic PM2.5 exposure exacerbates valproic acid-induced autism-like behaviors in murine models, identifying CTNNB1, PTEN, CCR2, AKT1, and mTOR as potential core mediating genes." (PMID 41304474, 2025).
autoimmune PAP (1 paper, 2024). "Furthermore, the alveolar macrophages observed in patients with CCR2 deficiency (P1 and P6) were not large or foamy and did not resemble those seen in patients with autoimmune PAP (inset)." (PMID 38157855, 2024).
autoimmune thyroid disease (1 paper, 2021). Inflammatory disease of the thyroid gland due to autoimmune responses leading to lymphocytic infiltration of the gland. "As for the CCR2 low-expression group, the genes were abundant in ‘autoimmune thyroid disease’, ‘graft versus host disease’, and ‘chemokine signaling pathway’." (PMID 34251980, 2021).
autoimmune vasculitis (1 paper, 2025). An autoimmune form of vasculitis. "Cardiac tissue-resident macrophages are reported to promote autoimmune vasculitis by activating the CCL2/CCR2 axis, which can start the cascade of proinflammatory events as well as recruit circulating CCR2+monocytes and neutrophils." (PMID 39820040, 2025).
B-cell lymphomas (1 paper, 2021). "In addition, CCR2 is expressed on a small fraction of human B lymphocytes in peripheral blood (PB) and tonsils and the cell-surface expression of CCR2 in different types of B-cell lymphomas can be rather high in patients with chronic lymphocytic leukemia (CLL)." (PMID 34804061, 2021).
Blastomyces dermatitidis infection (1 paper, 2018). "In addition, studies of pulmonary Blastomyces dermatitidis infection have demonstrated that inhibition of CCR2+ Ly6C+ influx is a mechanism of virulence employed by other fungi." (PMID 29317510, 2018).
Brain atrophy (1 paper, 2016). Partial or complete wasting (loss) of brain tissue that was once present. "At this point, the tissue damage measured by brain atrophy tended to be higher in CCR2−/− (13.2 ± 3.2 mm3) mice as compared to WT mice (7.7 ± 3.5 mm3, p = 0.2, n = 5–6/group)." (PMID 27814740, 2016).
calcification (1 paper, 2022). Process by which organic tissue becomes hardened by the physiologic deposit of calcium salts. "In addition, AIF-1 could mediate elevations in serum phosphorus, FGF23, PTH, and vascular CCR2 as demonstrated in the present study, which was previously thought to be pathways of NF-κB causing vascular calcification." (PMID 35937793, 2022).
cardiac interstitial fibrosis (1 paper, 2024). "In contrast, an augmented influx of bone marrow-derived CCR2+ macrophages can replace part of the predominantly embryonic-derived CCR2− macrophages, release a large number of cytokines, promote fibroblast proliferation, and cause cardiac interstitial fibrosis." (PMID 39682749, 2024). "Accordingly, selective inhibition of CCR2+ macrophages was shown to inhibit left ventricular hypertrophy, ameliorate diastolic function, and reduce cardiac interstitial fibrosis and inflammation in HFpEF." (PMID 39682749, 2024).
carditis (1 paper, 2014). "Fundamental differences between strains have been reported previously in Lyme carditis studies comparing the effect of Stat1 and Ccr2 deficiencies on carditis-susceptible and carditis-resistant mouse strains." (PMID 24967703, 2014).
central obesity (1 paper, 2023). "A main effect of central obesity status revealed higher expression of CCR2 and CCR5 on total monocytes for all stages in participants with central obesity compared to participants who were lean (p ≤ 0.045, ES ≥ 0.66)." (PMID 38011590, 2023). "The relative migration of IM, NCM, CCR2+M, CCR2+CM, and CCR5+M was higher in participants with central obesity compared with participants who were lean (p ≤ 0.009; ES ≥ 0.90), but there was no main effect on the relative migration of M or CM (p ≥ 0.067; ES ≤ 0.61)." (PMID 38011590, 2023).
cerebellar ataxia (1 paper, 2023). A neurological syndrome characterized by clumsy and uncoordinated movement of the limbs, trunk, and cranial muscles. "Analysis for the cerebellar ataxia through the rotarod test revealed an improvement in both female and male npc1−/−_Ccr2–RFP/RFP double-mutant mice when compared with npc1−/−_Ccr2+/+-single-mutant mice." (PMID 37369603, 2023).